DLL4 (delta like canonical Notch ligand 4)
Description:
Involved in the Notch signaling pathway as Notch ligand. Activates NOTCH1 and NOTCH4. Involved in angiogenesis; negatively regulates endothelial cell proliferation and migration and angiogenic sprouting. Essential for retinal progenitor proliferation. Required for suppressing rod fates in late retinal progenitors as well as for proper generation of other retinal cell types (By similarity). During spinal cord neurogenesis, inhibits V2a interneuron fate.
Synonyms: Delta4; AOS6; hdelta2
Tractability: Antibody: a drug acting on it is in phase 2 or 3 trials; UniProt places it where antibodies can reach, with high confidence; its Gene Ontology location is reachable by antibodies, with high confidence; UniProt predicts a signal peptide or a membrane-spanning region.
Gene: Protein-coding gene on chromosome 15 (40,929,338 to 40,939,078, forward strand). Ensembl gene ENSG00000128917.
Subcellular location: Cell membrane
Pathways (Reactome):
Disease: Constitutive Signaling by NOTCH1 HD Domain Mutants; Constitutive Signaling by NOTCH1 HD+PEST Domain Mutants; Constitutive Signaling by NOTCH1 PEST Domain Mutants; Constitutive Signaling by NOTCH1 t(7;9)(NOTCH1:M1580_K2555) Translocation Mutant
Signal Transduction: Activated NOTCH1 Transmits Signal to the Nucleus; NOTCH2 Activation and Transmission of Signal to the Nucleus; NOTCH3 Activation and Transmission of Signal to the Nucleus; NOTCH4 Activation and Transmission of Signal to the Nucleus
Gene Ontology:
Molecular function: Notch binding; protein binding; receptor ligand activity; calcium ion binding
Biological process: aortic valve morphogenesis; cellular response to fibroblast growth factor stimulus; cellular response to vascular endothelial growth factor stimulus; negative regulation of blood vessel endothelial cell proliferation involved in sprouting angiogenesis; negative regulation of cell migration involved in sprouting angiogenesis; negative regulation of cell population proliferation; negative regulation of endothelial cell migration; negative regulation of gene expression; Notch signaling pathway; positive regulation of gene expression; ventral spinal cord interneuron fate commitment; angiogenesis; blood vessel remodeling; branching involved in blood vessel morphogenesis; cardiac atrium morphogenesis; cardiac ventricle morphogenesis; dorsal aorta morphogenesis; negative regulation of Notch signaling pathway; negative regulation of transcription by RNA polymerase II; pericardium morphogenesis; positive regulation of neural precursor cell proliferation; positive regulation of Notch signaling pathway; regulation of neural retina development; signal transduction; T cell differentiation; and 6 more
Cellular component: plasma membrane; membrane
Genetic constraint (gnomAD): Loss-of-function variants: 7 observed, 66.61 expected, observed/expected ratio (o/e) 0.11, 90% interval 0.059 to 0.2. The upper end of that interval is the gene's LOEUF score, 0.2, which puts it in group 1 of 6, group 1 being the genes least tolerant of losing a copy. Missense variants: 614 observed, 941.85 expected, observed/expected ratio (o/e) 0.65, 90% interval 0.61 to 0.7. Synonymous variants: 344 observed, 380.81 expected, observed/expected ratio (o/e) 0.9, 90% interval 0.83 to 0.99.
Homologues: Orthologues: macaque DLL4 (99% identical), pig DLL4 (93% identical), chimpanzee DLL4 (93% identical), rabbit DLL4 (93% identical), dog DLL4 (93% identical), guinea pig DLL4 (93% identical), mouse Dll4 (86% identical), rat Dll4 (86% identical), tropical clawed frog dll4 (61% identical), Drosophila melanogaster Ser (36% identical), Caenorhabditis elegans paml-1 (11% identical), Caenorhabditis elegans paml-2 (8% identical). Paralogues in human: DLL1 (50% identical), JAG2 (36% identical), JAG1 (36% identical), NOTCH4 (26% identical), DNER (23% identical).
Diseases named in the same sentence as DLL4 in open-access papers:
DLL4 is named in the same sentence as 201 diseases in open-access papers, as found by Europe PMC text mining. Sharing a sentence is not in itself a finding about the gene and the disease. The quoted sentences say what the papers report.
breast carcinoma (42 papers, 2011 to 2025). "In breast cancer, a high expression of DLL4 at mRNA and protein levels is associated with advanced tumor stages and poor differentiation." (PMID 35205828, 2022). "Targeting TNPs to tumor endothelium via anti-DLL4 antibody conjugation improved therapy sensitivity in high DLL4 allele hosts for two triple negative human breast cancer xenografts." (PMID 32373218, 2020). "The second modifier locus is linked with DLL4 and impacts breast cancer growth and metastasis by inducing dysfunctional angiogenesis." (PMID 31139207, 2019). "Subsequently, we extracted DLL4+ cancer cell subpopulations in single-cell transcriptomes and conducted subpopulation deconvolution mapping to multiple breast cancer datasets, such as TCGA and GEO." (PMID 41326912, 2025). "Delta like canonical notch ligand 4 (Dll4) affects angiogenesis within breast cancer and is a potential therapy target." (PMID 38858280, 2024). "A similar work demonstrated the anti-tumor role of Dll4 blockade in breast cancer mouse xenograft models, where combined treatment of anti-Dll4 antibody in combination with docetaxel led to tumor cell apoptosis, CSC phenotype and reversal of EMT." (PMID 38269089, 2023). "We conclude that TME-driven GPR81 upregulation supports Luminal A breast cancer cell aggressiveness at least in part via DLL4." (PMID 37993804, 2023). "We conclude that GPR81 upregulation in the tumor microenvironment supports breast cancer aggressiveness at least in part via DLL4 upregulation and remodeling of ECM composition and cell–cell and cell–matrix interactions." (PMID 37993804, 2023). "Two rat-based consomic xenograft (CXM) strains of breast cancer with different Dll4 expression levels and eight congenic xenograft strains were studied." (PMID 36900252, 2023). "As the most common ligands of Notch during angiogenesis that are also found to be upregulated in cancer, Dll4 and Jag1 have both been targeted for treatment of breast cancer tumors, with Dll4 being a more established focus point." (PMID 33381526, 2020). "This is achieved through the “tip and stalk” cell selection procedure and act of the Notch-1, -4, and Dll-4 proteins that are all profoundly involved in the development of breast cancer." (PMID 30111989, 2018). "Notch receptors (Notch 1, 3 and 4) and ligands (JAG1 and DLL4) were highly expressed in human breast cancers, contributing to the abnormal growth of breast cancer cells, when compared to normal breast tissues obtained from the margin of the tumor section." (PMID 30248941, 2018). "The results also show marked down-regulation in the expression of DLL4 in breast cancer cell lines and neuroblastoma cell lines when all are compared to a normal fibroblast cell line, HS27, used as control." (PMID 27542210, 2016). "As the results confirm, only the DLL4 promoter in human breast cancer cell line (MCF7) shows a positive correlation between low-level of DLL4 expression and the methylation state in the distal of promoter region and not in the proximal of promoter region." (PMID 27542210, 2016). "Recently, DLL4 was found to be overexpressed in axillary lymph node metastasis and was a good biomarker for poor prognosis in breast cancer." (PMID 27625789, 2016). "In breast cancer, high Dll4 expression by intratumoral endothelial cells was elucidated as an adverse prognostic factor of patient survival." (PMID 26755662, 2016). "In summary, H3L2 is an ideal humanized antibody that blocks DLL4/Notch pathway against breast carcinoma in vivo and it is a promising anti-tumor drug candidate for clinical studies." (PMID 27301650, 2016). "Expression of DLL4 and IL-1R tI were significantly different among the three breast cancer types (p=0.028 and 0.027, respectively)." (PMID 24716804, 2014). "Further, at least in the case of breast cancer, the degree of Dll4 expression correlated with outcome: tumors with high Dll4 in the vasculature progressed more rapidly." (PMID 21923938, 2011).
breast carcinoma (continued). "Herein, we used two rat-based CXM strains of breast cancer, SSIL2Rγ−(Dll4+) and SS.BN3IL2Rγ− (Dll4−), as well as eight congenic xenograft strains, CG1–CG8, to assess the impact of germline TME vascular heterogeneity on the signal intensity of DE-NIR imaging with systemically delivered ICG." (PMID 36900252, 2023). "Considering the positive correlation between DLL4 expression and metastasis development in breast cancer, the addition of selective anti-DLL4 approaches could be useful to treat or prevent metastatic tumors." (PMID 34680255, 2021). "Additionally, the treatment with an FK506-binding protein-like (FKBPL)-based peptide repressed a subpopulation of endocrine therapy-resistant CSC in ER+ breast cancer by interfering with DLL4 and Notch4 signaling." (PMID 34680255, 2021). "Anti-Dll4 antibody has also shown to inhibit breast cancer growth." (PMID 32211044, 2020). "Therefore, all of these studies suggest that DLL4 and Notch 4 are viable therapeutic targets for both triple negative and ER+ breast cancer treatment." (PMID 30975104, 2019). "It is possible that DLL4 may have tumor-promoting function in luminal breast cancer, which needs future careful evaluation." (PMID 30442981, 2019). "Furthermore, tumour and plasma levels of the Notch 1, 2, or 4 receptors and DLL4 ligand were positively correlated with nodal and distant metastases in breast cancer and shorter disease-free or overall survival compared to patients with high DLL4 levels." (PMID 30975104, 2019). "We did observe a correlation with DLL4 and poor prognosis in luminal A breast cancer patients." (PMID 30442981, 2019). "Blocking Dll4, the Notch ligand specifically involved in modulation of angiogenesis, has given promising results in interfering with cancer growth: administration of anti-Dll4 agents in breast cancer xenografts promotes excessive sprouting, which leads to unproductive angiogenesis." (PMID 25629006, 2014). "Majority of breast cancers were positive for Notch1, DLL4 and VEGF." (PMID 24716804, 2014). "TNBC showed lower levels of DLL4 and IL-1R tI compared to ER- and ER+ breast cancer." (PMID 24716804, 2014). "Thus far, tumor vascular Dll4 expression has been detected in many human tumor samples including kidney, bladder, colon, brain and breast cancer." (PMID 21923938, 2011). "The Notch signaling system that contains four Notch receptors (Notch1- Notch4) and five canonical ligands (Dll1, Dll3, Dll4, Jagged1 and Jagged2), plays important roles including carcinogenesis, cancer stem cell renewal, angiogenesis, and chemotherapy resistance in the progression of breast cancer." (PMID 33413403, 2021). "The DLL4-Notch signaling pathway typically operates downstream of VEGF and is crucial in angiogenesis in breast cancer." (PMID 40486870, 2025). "We observed that several genes including PTCH1, ATXN1, DLL4, SOX2 and DACH1 were differentially regulated in tbLCM-treated breast cancer cells as compared to those treated with tnLCM or BM control." (PMID 38581619, 2024). "GPR81 supports breast cancer aggressiveness, and in MCF-7 cells, this occurs at least in part via DLL4." (PMID 37993804, 2023). "Importantly, in MCF-7 breast cancer cells as a model of Luminal A subtype breast cancers, GPR81-regulated genes were significantly associated with multiple GO terms relating to extracellular matrix (ECM) and cell adhesion, including PCDH7, EPHA7, and the Notch ligand DLL4." (PMID 37993804, 2023). "Disrupting the interaction between DLL4 and Notch1 induces tumor cell apoptosis and inhibits cell proliferation and EMT in breast cancer." (PMID 35844785, 2022).
breast carcinoma (continued). "Another bispecific anti-DLL4/VEGF antibody, ABT-165, outperformed tumor response with single anti-VEGF treatment in preclinical models of glioma, breast cancer, and colon cancer alone and in combination with standard-of-care chemotherapy drugs." (PMID 34680255, 2021). "In mammary tumor cells, radiation stimulated EMT through the IL-6/JAK/STAT3 signaling axis, which upregulated JAG1, DLL4, and Notch2 transcripts, and GSI addition effectively attenuated migration and mesenchymal markers expression in the irradiated cells." (PMID 34680255, 2021). "After knocking down linc-OIP5 in breast cancer cells, JAG1 expression was downregulated while DLL4 expression was upregulated in co-cultured HUVECs, rendering the production of fewer blood vessels." (PMID 32046779, 2020). "To investigate the details of an association between DNA methylation and CTCF in DLL4 gene regulation, we treated another breast cancer cell line, MDA231, which has a silenced DLL4 gene expression, with increasing concentrations of 5′-aza-dC for 3 days." (PMID 27542210, 2016). "This implies a possible karyotype-phenotype correlation with respect to DLL4 in LFS and breast cancer initiation and progression." (PMID 27542210, 2016). "The expressions of PCDH12, SLIT3, ACVRL1 and DLL4 not merely relate to the type and proportion of immune cells, but also contribute to the prognosis of breast cancer." (PMID 35953532, 2022). "Moreover, in human breast cancer, ESM1 was correlated with DLL4 in the GEPIA database (R = 0.34, p = 0) and DLL4 was increased in ESM1-treated HUVEC cells." (PMID 36428773, 2022). "In mouse breast cancer models, Dll4 monoclonal antibody induced the formation of nonfunctional blood vessels in tumor tissues and inhibited the growth of breast cancer." (PMID 31093499, 2019). "Dll-4 is found in the region of the endothelial cells participating in angiogenesis via “tip and stalk” procedure, obeying VEGF signals, and is found to be overexpressed in breast cancer." (PMID 30111989, 2018). "Surprisingly, the results show that the expression of most of these genes and especially DLL4, is dysregulated in LFS cell lines as well as in breast cancer cell line (MCF7) and neuroblastoma cell line (IMR32) when compared to normal foreskin human fibroblast cell line, HS27." (PMID 27542210, 2016). "OMP-305B83 generated by this platform is a BsAb targeting Notch pathway ligand delta-like ligand 4 (DLL4) and VEGF, which is undergoing a phase 1a clinical study for patients with previously treated solid tumors (including ovarian cancer, endometrial cancer, breast cancer, and pancreatic cancer)." (PMID 30886871, 2019). "To this end, when MCF7 breast cancer cells were treated with a STAT3 inhibitor or DMSO and radiated afterwards, we observed that the inactivation of STAT3 sharply attenuated the radiation-induced Notch2 (NICD2), Jagged1 and DLL4 mRNA expression and protein levels." (PMID 27462787, 2016). "Indeed, a bispecific anti-DLL4–anti-VEGF antibody notably improved the effects of paclitaxel on tumor growth inhibition and spontaneous lung and lymphatic node metastasis in a xenograft model of breast cancer, giving a good advantage over addition of anti-VEGF alone." (PMID 34680255, 2021). "Moreover, stromal DLL4 expression was not as remarkable as previously reported in breast cancer; therefore, the pattern of DLL4 expression in gastric cancer may be different from that of breast cancer." (PMID 23898884, 2013). "Having shown the relevance of Dll4 expression on BM-VPC for EC behavior in vitro, next we investigated whether these effects were also observed in vivo during tumor growth and specifically dependent on Dll4 expression by BM-VPC using a xenograft tumor model of mouse breast carcinoma (HTH-k)." (PMID 21483741, 2011). "We evaluated the levels of TGF-β, EGF, FGF, DLL4, and VEGF in the peripheral blood and WF of breast cancer patients in the IORT and non-IORT groups." (PMID 35681234, 2022).
breast carcinoma (continued). "DLL4, Notch1, IL-1R tI and VEGF were expressed in almost all breast cancer tissues irrespective of AR status." (PMID 24716804, 2014). "Here we show that NILCO components (Notch1, Notch4, JAG1, DLL4, leptin, OB-R, IL-1R tI) and target molecules (VEGF and VEGFR2) were co-expressed in breast cancer tissues, irrespective of ER, PR and, HER2 statuses." (PMID 24716804, 2014).